LNCSRLR (lncRNA sorafenib resistance in renal cell carcinoma associated)
Synonyms: lncRNA-SRLR
Gene: Long non-coding RNA gene on chromosome 3 (146,066,344 to 146,069,185, reverse strand). Ensembl gene ENSG00000240032.
Diseases named in the same sentence as LNCSRLR in open-access papers:
LNCSRLR is named in the same sentence as 1 disease in open-access papers, as found by Europe PMC text mining. Sharing a sentence is not in itself a finding about the gene and the disease.
LNCSRLR shares sentences with these, for which no sentence is quoted: tumor (1 paper).